TP53TG3C (TP53 target 3C)
Gene: Protein-coding gene on chromosome 16 (33,194,226 to 33,196,858, forward strand). Ensembl gene ENSG00000205457.
Subcellular location: Cytoplasm; Nucleus
Subcellular location (Human Protein Atlas): Centriolar satellite
Gene Ontology:
Cellular component: cytoplasm; nucleus
Homologues: Paralogues in human: TP53TG3 (100% identical), TP53TG3B (100% identical), TP53TG3D (100% identical), TP53TG3E (100% identical), TP53TG3F (100% identical).